FOXP3 (forkhead box P3)
Diseases named in the same sentence as FOXP3 in open-access papers (continued):
Sharing a sentence is not in itself a finding about the gene and the disease.
Obesity (49 papers, 2011 to 2025). Accumulation of substantial excess body fat. "Regarding BMI, obesity was associated with a lower percentage of IL‐10+FoxP3+CD4+ T‐cells only in patients with severe AA when compared to other patients and the control group." (PMID 35734271, 2022). "In men, all associations between obesity and FoxP3 low tumors, except for WHR, were retained, and further confirmed in the test for heterogeneity for hip circumference and BFP." (PMID 31741761, 2019). "Obesity was all over significantly associated with risk of CRC with low density of FoxP3+ T cells and low programmed cell-death protein 1 (PD-L1) expression on tumor cells, but with high density of CD8+ T cells and CD20+ B cells." (PMID 31741761, 2019). "In women, significant trends for associations of obesity with FoxP3 low tumors were observed for weight, hip and BMI." (PMID 31741761, 2019). "Furthermore, significant associations were found between obesity and risk of tumors with low infiltration of FoxP3+ T cells, but with risk of tumors with high infiltration of CD8+ T cells and CD20+ B cells." (PMID 31741761, 2019). "C57Bl/6J Foxp3GFP reporter mice, which are more prone to diet-induced obesity than Balb/c mice, likewise had significantly reduced frequencies of hypothalamus-residing Foxp3+GFP+Tregs when maintained on the HFHS diet." (PMID 40113758, 2025). "The loss of Foxp3+ Treg cells and chronic inflammation in VAT are well-established hallmarks of insulin resistance and obesity pathogenesis." (PMID 41346616, 2025). "The role of FoxP3+ Treg lymphocytes in obesity is still controversial and limited in human studies, especially in children." (PMID 37859769, 2023). "Tregs expressing Foxp3 trended towards being reduced in proportion by obesity and remain low following WL and WC." (PMID 35618862, 2022). "As previously reported, obesity resulted in a significant decrease in the percentage of circulating CD4+CD25+Foxp3+ regulatory T cells but a decreased proportion of peripheral blood monocytes (F4/80+ CD11b+ and CD11b+) compared to lean controls." (PMID 35472214, 2022). "Systemically, we found decreased percentages of CD14+CD16neg classical monocytes and Foxp3+ regulatory T cells in ccRCC subjects with obesity." (PMID 32469992, 2020). "In conclusion, obesity, measured as several anthropometric factors, was associated with risk of CRC with low density of tumor-infiltrating FoxP3+ T cells, but with high density of B cells and cytotoxic T cells in both sexes." (PMID 31741761, 2019). "In-vivo administration of β3 adrenergic receptor agonist CL-316243, which was once used for treatment of obesity and type 2 diabetes, enhanced abundance of Foxp3+ CD4+ T cells in inguinal lymph nodes as well as in adipose tissues, including BAT, SAT, and VAT." (PMID 30323806, 2018). "Specifically, reduced percentages of CD4(+)Foxp3(+) Treg cells were found in the abdominal fat of mice with genetic or diet-induced obesity." (PMID 27851820, 2016). "Obesity results in adipose-resident FoxP3+ Treg depletion and gain-of-function experiments to expand their numbers improved insulin sensitivity." (PMID 24710396, 2014). "In humans, both lowered Foxp3 expression and increased Foxp3 expression in the adipose tissue has been shown to accompany obesity." (PMID 24069022, 2013). "The anti-inflammatory action of Foxp3+ T cells (Tregs) has been proposed to alter insulin sensitivity, as obesity is accompanied by both a reduction in the proportion of this T cell population and the development of insulin resistance." (PMID 23562076, 2013). "These adoptive transfer model data showed that probiotic-mediated protection from obesity resided in functions of Foxp3+ regulatory T cells." (PMID 23874682, 2013). "Foxp3+ T cells were recently proposed to contribute to metabolic homeostasis and its dysregulation in obesity." (PMID 23562076, 2013).
Obesity (continued). "The Foxp3+ Tregs are negative regulators of inflammatory responses and recent studies have indicated that Tregs can inhibit obesity-related inflammation and insulin resistance in mice." (PMID 21966503, 2011). "Moreover, oral administration of A. muciniphila to high-fat diet (HFD)-fed mice increases the level of Foxp3+ Tregs in the adipose tissue, leading to the attenuation of obesity-induced local and systemic inflammation." (PMID 39683507, 2024). "Our data also showed significant increase in the levels of TNF-β, IL-5, PTX3 in T1DM, T2DM and obesity groups in comparison to infected control group, whilst the levels of FOXP3 and IL-10 were increased in the infected groups in comparison to their noninfected controls." (PMID 37296126, 2023). "It is possible that modulation of FoxP3+ Treg lymphocytes in obesity may be a promising alternative treatment." (PMID 37859769, 2023). "Assessing the effects of obesity on the immune contexture of various murine tissues by flow cytometry revealed that diet-induced obesity (DIO) significantly elevated the abundance of FoxP3+ Tregs with leukocyte pools, particularly in lung and lymph node cells." (PMID 36289552, 2022). "IL-33 treatment contributes to homeostasis in the adipose tissue by facilitating the differentiation and maintenance of Foxp3+ST2+ Treg cells and ILC2 in visceral adipose tissue, an immunomodulatory effect that can contribute towards down-regulating obesity-associated inflammation." (PMID 35807067, 2022). "In our study, we found upregulated Th17 (IL-17) and downregulated Treg cell marker (Foxp3) in the model mice, suggesting that Treg/Th17 imbalance might also occur to obesity-induced IR mice." (PMID 33781239, 2021). "In this study, the percentage of CD4+IL-17+ T cells tended to be higher and that of CD4+CD25+Foxp3+ T cells was higher in purified T cells from the HFD groups compared with the CON groups; however, the CD4+IL-17+ T cells/CD4+CD25+Foxp3+ T cells ratio was unaffected by obesity." (PMID 33670988, 2021). "Obesity-associated metabolic activity might result in PD-L1 expression, the suppression of CD8 + TIL counts, and the recruitment of Foxp3 + TILs, and these processes are considered to be involved in ICC progression." (PMID 33712681, 2021). "Moreover, upregulated miR-23b-3p reversed the effects of acacetin on downregulating IL-17 and upregulating Foxp3 in the mice with obesity-induced IR." (PMID 33781239, 2021). "The herein demonstrated associations between obesity and risk of tumors with high density of CD8+ cytotoxic lymphocytes, in particular in men, but with low density of FoxP3+ regulatory T-cells, suggest a differential relationship of obesity with different subsets of T lymphocytes." (PMID 31741761, 2019). "In obesity, the T cell population in adipose tissue is altered: proinflammatory Th1 T cell numbers substantially increase and there is a decline in the proportion of anti-inflammatory Foxp3+ Treg cells." (PMID 23562076, 2013). "Foxp3-positive regulatory T cells are highly enriched in the abdominal fat of normal mice, exerting anti-inflammatory effects, but are markedly reduced in number in diet-induced obesity." (PMID 22615812, 2012). "Similarly, adipose tissue Helios+ Foxp3+ Tregs were significantly decreased in response to obesity." (PMID 33256137, 2020). "FOXP3 was lower in VAT ARTs of obese vs. lean subjects, consistent with the decrease in AT Treg abundance in obesity." (PMID 36153324, 2022). "Obesity induced by HFD increased the CD8+/CD4+ ratio (p = 0.020), while reducing the population of CD4+ T cells (p = 0.027) and of Foxp3+ Tregs (p = 0.001) within the CD3+ CD4+ T cell population in adipose tissue compared to the SD." (PMID 26161548, 2015). "Adipose tissue macrophages (ATM) are primary contributors to obesity-related inflammation and the derived insulin resistance, but their effector function is suppressed by CD4+CD25+Foxp3+ regulatory T cells (Treg)." (PMID 23166823, 2012).
Obesity (continued). "The onset of obesity, however, triggers a shift in the VAT from an anti-inflammatory type 2 to a pro-inflammatory type 1 environment, accompanied by a marked reduction in the Foxp3+ Treg cell compartment." (PMID 41346616, 2025). "The higher transcription of mRNA FOXP3 and IL-10 (Treg markers), accompanied by a high transcription of TBX21 and IFNG (Th1 markers), GATA3 and IL-4 (Th2 markers) indicated the inflammatory status in the group with obesity and an altered Treg function." (PMID 37215211, 2023). "In obese subjects, Foxp3 mRNA levels were higher in SAT than in VAT, and the relative drop in Treg cells in VAT vs. SAT was positively correlated with BMI, suggesting that VAT Treg cells are negatively correlated with obesity in humans." (PMID 30323806, 2018). "In addition, Akkermansia ameliorates HFD induced obesity, metabolic endotoxemia, and glucose homeostasis via change of microbial metabolites, such as SCFA and interference of Foxp3 regulatory T cells." (PMID 28545248, 2017). "On the other hand, similar to our obesity study we found a significantly (p = 0.0002) lower proportion of natural killer (NK) cells (i.e., both CD56 bright and dim cells) and higher Tregs (CD4 + CD127low/-CD25 + FoxP3 + cells), suggesting a potentially poorer ability to kill cancer cells." (PMID 33173057, 2020). "The analysis of the immune cells in the lung tissue revealed that obesity did not affect the number of total inflammatory cells, CD4+ T cells, or the Foxp3+ Tregs in the lungs." (PMID 33256137, 2020).
helminth infections (46 papers, 2007 to 2025). "In the case of Schistosoma mansoni, infection is associated with elevated numbers of FOXP3‐expressing Tregs, and these cells are also more active during helminth infection as indicated by expression of programmed cell death protein 1 (PD‐1) and CD45RO." (PMID 32153025, 2020). "Interestingly, both FOXP3−IL‐10+ Tr1 and FOXP3+ Tregs are associated with an isotype switch from IgE to IgG4 in vitro and during helminth infection." (PMID 32153025, 2020). "In order to assess the impact of IL-6 deficiency on Treg-cell function in vivo following helminth infection, we performed Foxp3 staining in concert with intracellular cytokine staining at a time-point when effector cell responses were dysregulated in IL-6−/− mice (day 7)." (PMID 24185641, 2014). "PGRN further exerts its anti-inflammatory influence by inducing naïve T cells to transform into FOXP3-expressing regulatory T cells (Tregs), a lymphocyte type that is underrepresented in inflammatory diseases but the presence of which is a hallmark of helminth infections." (PMID 26485648, 2015). "Studies have also demonstrated that ICOS can promote the proliferation and function of Foxp3+ Treg cells during various helminth infections." (PMID 40316996, 2025). "Helminth infections had been shown to increase the amount of colonic Tregs and Foxp3 expression, both of which were critical in maintaining the immunological balance in the colon." (PMID 38166140, 2024). "It has been observed that helminth infections elevate the number of colonic Tregs and Foxp3 expression that are important in maintaining the immune balance in the colon." (PMID 34336843, 2021). "For instance, during intestinal helminth infection, Foxp3+ Treg cells are actively induced by the pathogen leading to a state of hyporesponsiveness, which is key for parasite persistence." (PMID 33193456, 2020). "Meanwhile, CD4+CD25+FoxP3+ Tregs play an important role in parasite-mediated down-regulation of the immune system, and most helminth infections result in recruitment of Tregs." (PMID 29843794, 2018). "Foxp3-expressing Treg cells are critical to maintaining immune homeostasis by minimizing tissue pathology, while modulating host immune response against helminth infections." (PMID 29216911, 2017). "In summary, this work has demonstrated that the character of the initial immune response invoked by S. mansoni parasites in C57BL/6 mice contrasts with the responses to other parasitic helminth infections, which promote rapid Foxp3+ Treg cell responses." (PMID 26195548, 2015). "Rapid expansion of Foxp3+ Treg cells has been clearly shown to occur in the early phase of several helminth infections, such as nematode parasites in mouse models, resulting in impaired protective immunity." (PMID 26195548, 2015). "Foxp3+ regulatory T (Treg) cells play a key role in suppression of immune responses during parasitic helminth infection, both by controlling damaging immunopathology and by inhibiting protective immunity." (PMID 26195548, 2015). "In spite of the complexity of regulatory cell types, CD4+CD25+Foxp3+ Treg cells are the most prominent population of immunoregulatory cells known so far to be induced during helminth infections." (PMID 23365718, 2013). "Experimental evidence points to the possible involvement of regulatory T cells in other chronic helminth infections, such as those caused by hookworm, where there is an increased number of circulating CD4+CD25+Foxp3+ T cells, compared to healthy individuals." (PMID 24348679, 2013). "Generation of Treg cells with elevated expression of Foxp3 during helminth infection has also been demonstrated." (PMID 23365718, 2013). "Little is yet known regarding the co-stimulatory environment that favours the development of Foxp3+ Treg-cell responses during helminth infections." (PMID 23319295, 2013). "On the other hand, CD4+CD25+Foxp3+ Treg cells have been shown to play key roles in animals and humans with helminth infections." (PMID 21912714, 2011).
helminth infections (continued). "An increase in peripheral CD4+CD25+Foxp3+ T cells has been observed in a number of infectious diseases including tuberculosis, hepatitis C and helminth infections, as well as human and murine malaria infection." (PMID 19680449, 2009). "Tregs, characterized by the expression of Foxp3, play pivotal roles in helminth-mediated gut immune regulation by modulating immune responses, reducing inflammation, and maintaining gut homeostasis during helminth infections." (PMID 40713878, 2025). "Notably, upon helminth infection, selective expansion of Foxp3+ Helios+ tTreg as well as Foxp3+ Helios- pTreg cells has been described, suggesting that control of anti-helminth immunity involves multiple pathways of Treg cell recruitment." (PMID 33193456, 2020). "We found that helminth infection modestly increased the frequency of FoxP3+ CD25+ Tregs within the CD4+ T cell compartment in the auricular LN draining the ear skin, and that 2 doses of anti-CD25 significantly reduced the frequency of Tregs in both uninfected and Hb infected mice." (PMID 32508831, 2020). "The results are consistent with other helminth infections that stimulated Foxp3+ Treg cells." (PMID 31703440, 2019). "Different helminth infections, such as Heligmosomoides polygyrus, Schistosoma japonicum, Schistosoma mansoni, and Brugia malayi are known to provoke an increased number of Foxp3+ Tregs." (PMID 31703440, 2019). "Adding to previous reports that have defined a restraining role for IL-4Rα on Foxp3+ Treg cells in vivo, we now present complementary evidence indicating that this receptor is equally needed, in full, in vivo for Foxp3+ Treg cell ability to control inflammation during helminth infections." (PMID 30379806, 2018). "Thus we now tackled the role of FoxP3+ Tregs and FoxP3+‐Treg‐regulated immune response in contributing to the control of this helminthic infection." (PMID 28621034, 2017). "Thus, the importance of Foxp3+ Treg cell responses during helminth infections can differ depending on the mouse strain, with Foxp3+ Treg cells potentially playing a lesser role in C57BL/6 mice." (PMID 26195548, 2015). "To determine whether ICOS is required for the generation of Foxp3+ Treg-cell responses during helminth infection, we infected C57BL/6 ICOS−/−33 and WT mice with H. polygyrus or S. mansoni." (PMID 23319295, 2013). "Foxp3+ Treg cells expand during helminth infections and may promote the survival of helminths as well as limit immune-driven pathology." (PMID 23637593, 2013). "Thus, ICOS regulates Type 2 immunity in a tissue-specific manner, and plays a key role in driving Foxp3+ Treg-cell expansion and function during helminth infections." (PMID 23319295, 2013). "Thus, ICOS controls Type 2 immunity in a tissue-specific manner, and plays a key role regulating Foxp3+ Treg-cell induction, maintenance and function during helminth infection." (PMID 23319295, 2013). "In this study we tested the hypothesis that ICOS is required for the induction and function of Foxp3+ Treg-cell responses during helminth infection." (PMID 23319295, 2013). "Alternatively activated macrophages that are expanded during helminth infections have been shown to promote Foxp3+ Treg differentiation and, by up-regulating arginase 1, play an important immune regulation and tissue repair role, respectively, by competing for L-arginine and generating proline." (PMID 23637593, 2013). "Thus, ICOS regulates Type 2 immunity in a tissue-specific manner, and plays a key common role driving Foxp3+ Treg-cell expansion and function during distinct helminth infections." (PMID 23319295, 2013). "However, our data demonstrates that helminth infection-expanded FoxP3+ Tregs clearly regulate coincident pro-fibrotic Th2 processes in the colon." (PMID 21858239, 2011).